BTK (Bruton tyrosine kinase)
Diseases named in the same sentence as BTK in open-access papers (continued):
Sharing a sentence is not in itself a finding about the gene and the disease.
chronic lymphocytic leukemia (continued). "Carl H. June reported co-treatment with the Bruton tyrosine kinase (BTK) inhibitor ibrutinib along with anti-CD19 CAR T cells improves responses against mantle cell lymphoma and B cell chronic lymphocytic leukemia." (PMID 32123937, 2020). "Ibrutinib is a Bruton’s tyrosine kinase (BTK) and interleukin-2-inducible kinase (ITK) inhibitor used for treating chronic lymphocytic leukaemia (CLL) and other cancers." (PMID 32025027, 2020). "Ibrutinib, an irreversible inhibitor of BTK, is now approved for the treatment of chronic lymphocytic leukemia (B-CLL), mantle cell lymphoma, marginal zone lymphoma, small lymphocytic lymphoma and Waldenström’s macroglobulinemia." (PMID 30700842, 2019). "Bruton’s tyrosine kinase (BTK) is an enzyme expressed in B cells, macrophages, and mast cells, and targeting BTW in combination with ibrutinib was shown to be effective in chronic lymphocytic leukemia, Mantle cell lymphoma, and Waldenstrom’s macroglobulinemia." (PMID 30158932, 2018). "The Bruton’s tyrosine kinase (BTK) inhibitor ibrutinib, which antagonizes B cell receptor (BCR) signals, demonstrates remarkable clinical activity in chronic lymphocytic leukemia (CLL)." (PMID 29301866, 2018). "Ibrutinib, a Bruton’s tyrosine kinase (BTK) inhibitor, inhibits mast cell degranulation and has been approved for the treatment of chronic lymphocytic leukemia and mantle cell lymphoma." (PMID 29891787, 2018). "In particular, the orally administered BTK inhibitor ibrutinib, which forms a covalent bond with a cysteine residue in the BTK active site, was also approved for first-line treatment of patients with chronic lymphocytic leukemia (CLL) and small lymphocytic leukemia (SLL) in 2016." (PMID 29455639, 2018). "The Bruton tyrosine kinase (BTK) inhibitor, ibrutinib, has been approved for the treatment of chronic lymphocytic leukemia, mantle cell lymphoma, and Waldenstroms macroglobulinemia." (PMID 27776353, 2017). "Ibrutinib, an orally administered selective inhibitor of BTK, has demonstrated impressive efficacy in the treatment of B cell malignancies and is FDA approved as a therapy for mantle cell lymphoma and chronic lymphocytic leukemia." (PMID 27363832, 2016). "Ibrutinib and osimertinib are representative examples of covalent inactivators of Bruton tyrosine kinase (BTK) for the treatment of mantle cell lymphoma and chronic lymphocytic leukemia and epidermal growth factor receptor (EGFR) for the treatment of non-small-cell lung cancer, respectively." (PMID 38891780, 2024). "We describe a non-genetic adaptation to BTK inhibitor therapy in chronic lymphocytic leukemia that involves Akt activation via FoxO1/Rictor axis." (PMID 39436708, 2024). "As a result, BTK is a target for clinical intervention for diseases such as mantle cell lymphoma (MCL), chronic lymphocytic leukemia (CLL), Waldenström macroglobulinemia (WM), small lymphocytic lymphoma, marginal zone lymphoma, and chronic graft-versus-host disease." (PMID 37651403, 2023). "BTK resynthesis was faster in patients with chronic lymphocytic leukemia (CLL) than in healthy volunteers; therefore, it is hypothesized that complete/sustained BTK occupancy may improve the efficacy outcomes." (PMID 37845755, 2023). "A recent study examining immune dysfunctions in chronic lymphocytic leukemia (CLL) found that PD-1 triggering on monocytes resulted in impaired glycolysis, phagocytosis and Bruton’s tyrosine kinase (BTK) signaling and that blocking the PD-1 pathway reverted the metabolic dysfunction." (PMID 35371563, 2022). "Ibrutinib, a small molecule inhibitor of Bruton’s tyrosine kinase (BTK), has been successfully used in the treatment of refractory AIHA among chronic lymphocytic leukaemia patients and could be an option to consider in PID." (PMID 36052091, 2022).
chronic lymphocytic leukemia (continued). "Chaetoglobosin A (ChA), a fungal extract produced by Penicillium aquamarinium, could effectively prevent the activation of chronic lymphocytic leukemia (CLL) cells and thus sensitize them to the PI3K and Bruton's tyrosine kinase (BTK) inhibitors treatment." (PMID 36104717, 2022). "Ibrutinib, a small-molecule inhibitor of Bruton’s tyrosine kinase (BTK) and bone marrow X-linked (BMX) non-receptor tyrosine kinase, has been approved for the treatment of patients with chronic lymphocytic leukemia (CLL) and mantle cell lymphoma." (PMID 35954371, 2022). "Specifically, BTK is a tissue specific target for inhibition in various B-cell lymphomas including diffuse large B-cell lymphoma (DLBCL) and chronic lymphocytic leukemia (CLL); proliferation of these lymphomas strictly depends on the activation of the BTK signaling cascade." (PMID 34249912, 2021). "A case report demonstrated M. chelonae skin and soft tissue infection in a patient with chronic lymphocytic leukemia (LLC) who was using ibrutinib, an oral drug, which acts by inhibiting Bruton tyrosine kinase (BTK) for the treatment of various malignant B-cell diseases." (PMID 34113346, 2021). "Furthermore, the second-generation BTK inhibitor acalabrutinib has also been approved by the FDA for treatment of mantle cell lymphoma, and chronic lymphocytic leukemia/small lymphocytic lymphoma." (PMID 34063667, 2021). "Additionally, HSP90 showed to stabilize BCR kinases such as Bruton tyrosine kinase (BTK), SYK, LYN and AKT in chronic lymphocytic leukemia cells." (PMID 33815422, 2021). "It is the most studied BTK inhibitor and is FDA approved for chronic lymphocytic leukemia." (PMID 35008785, 2021). "Bruton tyrosine kinase (BTK) inhibitors have demonstrated a high degree of efficacy in the treatment of B cell malignancies characterized by constitutive B cell receptor activation, including chronic lymphocytic leukemia/small lymphocytic lymphoma (CLL/SLL)." (PMID 32393328, 2020). "Ibrutinib is a covalent inhibitor of Bruton's tyrosine kinase (BTK) and it is indicated for the treatment of patients with mantle cell lymphoma (MCL), chronic lymphocytic leukemia, small lymphocytic lymphoma, Waldenström's macroglobulinemia and marginal zone lymphoma." (PMID 32595510, 2020). "Ibrutinib, an irreversible Bruton Tyrosine Kinase (BTK) inhibitor, has revolutionized Chronic Lymphocytic Leukemia (CLL) treatment, but resistances to ibrutinib have emerged, whether related or not to BTK mutations." (PMID 33298182, 2020). "Ibrutinib (PCI-32765, Imbruvica), the first Food and Drug Administration (FDA)-approved covalent irreversible BTK inhibitor, has been used successfully for the treatment of patients with relapsed or refractory mantle-cell lymphoma (MCL) and chronic lymphocytic leukemia (CLL)." (PMID 33113810, 2020). "BTK inhibitors were developed for the treatment of lymphoproliferative disorders: among them Ibrutinib is already FDA-approved for the treatment of mantle cell lymphoma, chronic lymphocytic leukemia and Waldenström macroglobulinemia." (PMID 31200752, 2019). "Inhibitors of the Bruton’s Tyrosine Kinase (BTK) and BCL2 (B-cell lymphoma 2) are two highly effective classes of agents in the management of patients with chronic lymphocytic leukemia (CLL) either as single agents or in combination." (PMID 41488721, 2025). "Ibrutinib: Ibrutinib is an irreversible Bruton’s tyrosine kinase (BTK) inhibitor that impedes B-cell proliferation and survival, and is commonly used in the treatment of various malignancies, including mantle cell lymphoma, chronic lymphocytic leukemia, and Waldenstrom’s macroglobulinemia." (PMID 41226426, 2025). "Ibrutinib, the first approved Bruton ́s Tyrosine Kinase (BTK) inhibitor, has shown potent clinical activity in a variety of B-cell malignancies and has been globally approved for the treatment of adult patients with Chronic Lymphocytic Leukemia (CLL) and Small Lymphocytic Lymphoma (SLL)." (PMID 40019563, 2025).
chronic lymphocytic leukemia (continued). "In 2017 and 2018, Bruton tyrosine kinase inhibitors and venetoclax were not available for front-line therapy of chronic lymphocytic leukemia in Croatia, and the combination of obinutuzumab and chlorambucil was the treatment of choice for unfit and elderly patients." (PMID 39767808, 2024). "Ibrutinib is a first-generation oral BTK inhibitor that has been clinically approved by the United States Food and Drug Administration (FDA) for the treatment of various B-cell malignancies, including chronic lymphocytic leukemia and small lymphocytic lymphoma." (PMID 39280007, 2024). "In addition, several non-C481 mutations have been observed in patients resistant to irreversible BTKi and, more recently, in relapsed chronic lymphocytic leukemia patients treated with the noncovalent BTK inhibitor pirtobrutinib." (PMID 36183831, 2022). "As a first-generation Bruton-kinase (BTK) inhibitor, ibrutinib was rapidly approved by the US Food and Drug Administration (FDA), firstly for the treatment of chronic lymphocytic leukemia (CLL)/small lymphocytic lymphoma (SLL) and mantle-cell lymphoma (MCL) in 2013 and 2014." (PMID 34640501, 2021). "The BTK inhibitor ibrutinib (PCI‐32765, Imbruvica) is a Food and Drug Administration‐approved drug for the treatment of a number of B cell cancers, including mantle cell lymphoma, chronic lymphocytic leukemia/small lymphocytic lymphoma, Waldenström's macroglobulinemia and marginal zone lymphoma." (PMID 31850638, 2020). "Bruton's tyrosine kinase (BTK) regulates the B-cell receptor (BCR) signaling pathway, which, in turn, plays a critical role in B-cell chronic lymphocytic leukemia (B-CLL) pathogenesis." (PMID 30416684, 2018). "In addition, inhibition of JAK2 or BTK, downstream effectors of CXCL12, inhibits integrin activation and suppresses tumor cell adhesion, survival, and spread in B-cell chronic lymphocytic leukemia (B-CLL)." (PMID 37047140, 2023). "Prior to aCLL, five patients received no treatment for CLL/small lymphocytic lymphoma (SLL), while the other patients received treatment, predominantly with BTK inhibitors." (PMID 38185521, 2023). "The Bruton’s tyrosine kinase (BTK) inhibitor ibrutinib has been a major advance for chronic lymphocytic leukemia (CLL) patients but it does not cure as a single agent, outcomes for patients who ultimately progress on it are poor, and strategies to improve its activity are needed." (PMID 34791813, 2021).
mantle cell lymphoma (232 papers, 2014 to 2026). Mantle cell lymphoma is a rare form of malignant non-Hodgkin lymphoma affecting B lymphocytes in the lymph nodes in a region called the ``mantle zone''. "Mantle cell lymphoma cells often acquire resistance to such therapy and continue to survive, commonly caused by mutations affecting the BTK protein." (PMID 37566089, 2023). "Syk plays also an important function in mantle cell lymphoma as a B cell receptor-associated kinase that activates the Bruton tyrosine kinase, a target of the ibrutinib inhibitor." (PMID 31817924, 2019). "Targeting BTK activity via small molecule covalent inhibitors like ibrutinib has also shown therapeutic efficacy in B cell malignancies associated with dysfunctional BCR signaling including mantle cell lymphoma (MCL) and chronic lymphocytic leukemia (CLL)." (PMID 30758770, 2019). "In Europe, brexucabtagene autoleucel was approved in December 2020 for the treatment of adult patients with relapsed or refractory mantle cell lymphoma (MCL) after ≥ 2 lines of systemic therapy including a Bruton's tyrosine kinase (BTK) inhibitor." (PMID 41311365, 2026). "Ibrutinib is a covalent inhibitor of Bruton’s tyrosine kinase (BTK), which is a crucial player in the development of mantle cell lymphoma (MCL) and is significantly upregulated in MCL cells." (PMID 40612109, 2025). "The near future in mantle cell lymphoma will see the employment of BTK inhibitors in frontline treatment." (PMID 40647536, 2025). "Zanubrutinib, another novel irreversible BTK inhibitor, is also approved for treating mantle cell lymphoma and demonstrates more potent anticancer activity compared to ibrutinib." (PMID 40346640, 2025). "In mantle cell lymphoma, the anticipation of BTK inhibitors in the first-line setting and the spreading of CAR-T-cells therapy completely changed the landscape." (PMID 40647536, 2025). "Comparative overview of BTK inhibitor–based regimens in mantle cell lymphoma: mechanisms, efficacy, and toxicity profiles." (PMID 40944468, 2025). "BTK inhibitors have been approved for the treatment of Mantle Cell Lymphoma (MCL) and other B-cell malignancies." (PMID 39161974, 2024). "It is worth mentioning that significant synergistic effects were observed when ironomycin combined with doxorubicin, BH3 mimetics, and Bruton’s tyrosine kinase (BTK) inhibitors in mantle cell lymphoma." (PMID 39834804, 2024). "Bruton tyrosine kinase (BTK) is involved in B cell development and maturation and plays a role in B cell malignancies such as mantle cell lymphoma." (PMID 38530400, 2024). "These agents have specific targets in various types of cancer, such as blocking Bruton’s tyrosine kinase (BTK) in mantle cell lymphoma, targeting mutant EGFR in NSCLC, or inhibiting ErbB2 in HER2-positive breast cancer, and Waldenström macroglobulinemia." (PMID 39404419, 2024). "In mantle cell lymphoma, intensive chemotherapy combined with BTK inhibitors and rituximab results in excellent outcomes, and the role of autologous transplantation is declining." (PMID 39513887, 2024). "Brexu-cel was the first CD19 CAR-T approved for the treatment of r/r mantle cell lymphoma, a B cell lymphoma with extremely poor prognosis when chemoimmunotherapy and Bruton’s tyrosine kinase (BTK) inhibitors are ineffective." (PMID 38727261, 2024). "Bruton’s tyrosine kinase (BTK) is a proven target in mantle cell lymphoma (MCL), an aggressive subtype of non-Hodgkin lymphoma." (PMID 36719376, 2023). "Ibrutinib, a BTK inhibitor, has been approved for the treatment of mantle cell lymphoma (MCL) and has been clinically evaluated as monotherapy or in combination in several malignancies including activated B cell-like (ABC) DLBCL." (PMID 36909156, 2023). "This review focuses on the feasibility of combining Bruton’s tyrosine kinase (BTK) inhibitors (BTKis) with chimeric antigen receptor (CAR) T-cell therapy in patients with relapsed or refractory (R/R) mantle cell lymphoma (MCL)." (PMID 35596920, 2022).
mantle cell lymphoma (continued). "Inhibition of p-BTK by ASK120067 was also observed in two other B-cell lymphoma cells: the mantle cell lymphoma (MCL) cell line Mino and Burkitt’s lymphoma cell line Ramos." (PMID 36588692, 2022). "Acalabrutinib, approved for Relapsed or Refractory Mantle-Cell Lymphoma, is an inhibitor of Bruton tyrosine kinase (BTK) acting by MAR with the thiol in Cys481." (PMID 36408214, 2022). "In the preclinical studies, NX-2127 degraded BTK effectively in both mantle cell lymphoma and diffuse large B-cell lymphoma (DLBCL) cells with DC50 of less than 5 nmol/L." (PMID 36046114, 2021). "To test this possibility, we used ibrutinib (PCI‐32765), an inhibitor that irreversibly binds to the C481 residue of BTK and inhibits Y223 stimulation and has been approved to treat mantle cell lymphoma and CLL." (PMID 31736210, 2020). "In ABC-DLBCL and Waldenström macroglobulinemia, ibrutinib is highly effective due to the activation of BTK via mutations in CD79B or the myeloid differentiation primary response gene 88 (MyD88), but in mantle cell lymphoma, these mutations are rare." (PMID 29907126, 2018). "Ibrutinib/PCI-32765, a novel potent inhibitor of BTK induces impressive responses in B-cell malignancies and has been approved for therapy of refractory mantle cell lymphoma." (PMID 24472371, 2014). "Resistance to Bruton tyrosine kinase inhibitors (BTKi) is inevitable in mantle cell lymphoma (MCL)." (PMID 42048618, 2026). "Additionally, Ganetespib enhances the sensitivity of mantle cell lymphoma (MCL) cells to the Bruton’s tyrosine kinase (BTK) inhibitor ibrutinib, particularly in resistant cancer cells." (PMID 41425251, 2025). "Similarly, mantle cell lymphoma (MCL) is characterized by constitutive phosphorylation of BTK and PLC-γ2, underscoring the importance of sustained BCR signaling in promoting malignant B cell survival and proliferation." (PMID 40861439, 2025). "Similarly, BTK plus PLCγ2 mutations, including mutations in the BTK amino acids L528, A428, and V416, were discovered in REC-1 mantle cell lymphoma (MCL) cell lines, which are resistant to vecabrutinib, pirtobrutinib, and fenebrutinib." (PMID 38469232, 2024). "Zanubrutinib, a highly selective inhibitor of BTK, could inhibit malignant B-cell proliferation and was approved for the treatment of mantle cell lymphoma." (PMID 38129902, 2023). "BTK plays a key role in B‐cell lymphomas and is a validated target for mantle cell lymphoma (MCL)." (PMID 37261210, 2023). "The signaling pathway mediated by the B-cell receptor (BCR) and its constituent, Bruton’s tyrosine kinase (BTK), is implicated in the pathogenesis of various B-cell malignancies, such as CLL, mantle cell lymphoma (MCL), and diffuse large B-cell lymphoma (DLBCL)." (PMID 37048814, 2023). "Ibrutinib, an inhibitor of Bruton's tyrosine kinase (BTK), is used to treat Waldenström's macroglobulinaemia, mantle cell lymphoma and lymphoblastic leukaemia, which also inhibits SDF‐1 induced AKT and MAPK activation, leading to the inhibition of the migration and proliferation of leukaemia cells." (PMID 34050566, 2021). "Although most of the new derivatives were weakly potent for BTK, 10, which incorporated a chloroacetyl warhead, demonstrated a low-nanomolar potency against BTK, with improved anticancer activity in a Mantle cell lymphoma cell line and improved selectivity over other kinases." (PMID 33479617, 2020). "Although Bruton’s tyrosine kinase (BTK) inhibitors (BTKi) have significantly improved patient prognosis, mantle cell lymphoma (MCL) is still considered incurable due to primary and acquired resistance." (PMID 38454120, 2024). "Single-cell sequencing of 15 patients with mantle cell lymphoma (MCL) receiving combined BTK inhibitor and CAR-T therapy revealed the importance of the HSP90-MYC-CDK9 axis in this treatment strategy." (PMID 39026380, 2024).